BMI1 (BMI1 proto-oncogene, polycomb ring finger)
Diseases named in the same sentence as BMI1 in open-access papers (continued):
Sharing a sentence is not in itself a finding about the gene and the disease.
lymphoma (38 papers, 2001 to 2024). A malignant (clonal) proliferation of B- lymphocytes or T- lymphocytes which involves the lymph nodes, bone marrow and/or extranodal sites. "BMI1 downregulates the expression of tumour-suppressor genes, such as p16INK4a and p14ARF, transgenic mice have a high predisposition to lymphomagenesis, subtypes of human lymphomas harbour BMI1 gene amplification and overexpression and it induces cell immortalisation." (PMID 16404435, 2006). "This relationship between c-myc and Bmi-1 was supported in a lymphoma mouse model: overexpression of both c-myc and Bmi-1 induced transformation primary embryo fibroblasts." (PMID 36726797, 2023). "The BMI-1 gene has been initially isolated as an oncogene, which cooperates with c-Myc in lymphoma experimental models." (PMID 34199929, 2021). "B-cell-specific Moloney murine leukemia virus integration site 1 (BMI1), the first functional gene in the PcG family, was identified in a mouse lymphoma in 1993." (PMID 33540760, 2021). "Genomic rearrangements of 10p12 leading to BMI-1 gain were recurrently found in patients with the transformation of CLL into aggressive lymphomas (Richter transformation) and MCL." (PMID 32197371, 2020). "Candidate genes involved in lymphoma-initiating cell maintenance include for example B-cell specific Moloney murine leukemia virus integration site 1 (BMI-1)." (PMID 32197371, 2020). "More importantly, we revealed a novel function of β-Asarone which acted as an inhibitor of the stem-like population in lymphoma cells by destabilizing Bmi1 via a proteasome-mediated mechanism." (PMID 31171917, 2019). "We revealed a novel function of β-Asarone which acted as an inhibitor of the stem-like population in lymphoma cells by destabilizing Bmi1 via a proteasome-mediated mechanism." (PMID 31171917, 2019). "As a key member of the PcG complex, Bmi-1 was originally identified as an oncogene cooperating with c-myc in murine lymphomas model." (PMID 29854278, 2018). "Bmi-1 was first isolated as an oncogene that cooperates with c-Myc in generating lymphomas in a murine model." (PMID 28424413, 2017). "The core PRC1 subunit BMI1 (also known as PCGF4 or RNF51) is required for cancer stem cell maintenance and its overexpression has been implicated in leukaemia and lymphoma." (PMID 28678185, 2017). "EphA7 silencing has been reported in several different human tumor types including lymphomas, and our data suggest BMI1 overexpression as a novel mechanism leading to EphA7 inactivation via H3K27 trimethylation and DNA methylation." (PMID 27533460, 2016). "The physiological functions of BMI1 in maintaining the self-renewal of stem cells likely contribute to its role in sustaining the self-renewal of cancer stem cells (CSCs) for lymphoma, neuroblastoma, and intestinal cancers." (PMID 26633535, 2015). "Originally identified as an oncogenic partner of c-Myc in murine lymphoma genesis, Bmi-1 is a member of the polycomb group transcriptional repressors." (PMID 22995409, 2012). "Bmi1 is a member of the polycomb group of transcriptional repressors that was initially identified as an oncogene cooperating with c-myc in a murine lymphoma model." (PMID 22509111, 2012). "The possible role of bmi-1 as a myc-collaborator in the FeLV-mediated induction of lymphoma was further examined by screening a large collection of FeLV-positive feline lymphomas representing different cohorts and involving different strains of FeLV." (PMID 21994802, 2011). "The BMI1 gene was first isolated as an oncogene that cooperated with c-Myc in generating lymphomas in a murine model." (PMID 19228380, 2009).
lymphoma (continued). "Furthermore, overexpression of BMI-1 has also been found in patients with myelodysplastic syndromes, chronic myelogenous leukemia, acute myeloid leukemia, and lymphoma." (PMID 38515119, 2024). "PCGF4/BMI1 has been identified as a tumor suppressor that represses the Ink4a/Arf gene locus directly in collaboration with c-MYC in a transgenic model of a mouse lymphoma." (PMID 39337298, 2024). "Furthermore, the upregulation of Bmi1 leads to the repression of cell-cycle regulators like p16INK4a/p19ARF and emersion of lymphoma in Bmi1 transgenic mice." (PMID 35685474, 2022). "BMI1 plays an important role in the development of malignant tumors including solid tumors of the brain, breast, colon, head and neck, liver, lung, and prostate, as well as hematologic malignancies including lymphoma and leukemia." (PMID 33540760, 2021). "Furthermore, overexpression of BMI1 was associated with drug resistance in hematological malignancies including myelodysplastic syndrome, chronic myeloid leukemia, AML, and lymphoma." (PMID 32742599, 2020). "BMI‐1 dysregulation leads to lymphoma and nonsmall cell lung carcinoma in humans." (PMID 27506447, 2016). "Bmi1 was the first known mammalian homologue of Drosophila polycomb proteins and was initially discovered through its ability to cooperate with c-Myc in the induction of lymphoma." (PMID 24614341, 2014). "In collaboration with several colleagues, the coincident involvement of flvi-2 (bmi-1) and myc was examined in a broad geographic sampling of naturally and experimentally induced FeLV-positive lymphomas that were heterogeneous with respect to the strain of FeLV involved." (PMID 21994802, 2011). "In mice, downregulation of one of the polycomb genes, bmi-1, leads to neurological alterations and severe proliferative defects in lymphoid cells, whilst bmi-1 overexpression, together with upregulation of myc-1, induces lymphoma." (PMID 11355949, 2001). "In summary, our data suggested that β-Asarone could be a potential drug for the treatment of lymphomas by increasing doxorubicin sensitivity via inhibiting NF-κB signaling and by targeting stem-like population to overcome drug resistance via reducing Bmi1 stability." (PMID 31171917, 2019). "Thus, our data implicated that β-Asarone could be a promising anti-cancer reagent by suppressing NF-κB activity and Bmi1 expression in lymphoma." (PMID 31171917, 2019). "B lymphoma Mo-MLV insertion region 1 homolog (BMI1), an essential protein of the polycomb repressive complex 1 (PRC1), was first identified as an oncogene, inducing lymphomas in mice by co-operating with c-MYC." (PMID 32343689, 2020). "RIM targeting of Bmi1 is largely a feature of B-cell lymphomas in the mouse, while Notch targeting predominates in the CD4+CD8+ lymphomas of Mmtv(d)-Myc mice." (PMID 24586197, 2014). "IC50 and ED50 values of PTC-209 positively correlated with those of PTC596 [r = 0.94 (P = 0.0004) for IC50 and r = 0.85 (P = 0.015) for ED50], respectively, supporting the idea that the anti-lymphoma activities of PTC-209 and PTC596 primarily depend on inhibition of BMI-1 expression." (PMID 29983879, 2018). "Many lymphoma cases showed high expression of EZH2, SUZ12, H3K27me3, and BMI1 in the tumor nuclei." (PMID 28412742, 2017). "Although previous study shows that Bmi1 might cooperate with NF-κB to regulate stem cell-like properties, our data indicated that Bmi1 might regulate stem cell-like properties independent of NF-κB signaling in lymphoma cells." (PMID 31171917, 2019).
neuroblastoma (38 papers, 2007 to 2025). Neuroblastoma (NB) is the most common solid, extracranial childhood tumor. "BMI1 also plays an essential role in the tumorigenesis of neuroblastoma in a process that is associated with a robust decrease in p16INK4A." (PMID 26633535, 2015). "Mechanistic studies have shown that Bmi1 promotes the proliferation of neuroblastoma cells and inhibits their differentiation by binding to the promoter regions of the tumor suppressor genes TSLC1 and KIF1Bβ." (PMID 41244073, 2025). "In the case of RB, the p16/pRB pathway is inherently inactivated and BMI1 overexpression can be driven by increased E2F activity as demonstrated by binding of E2F1 on BMI1 promoter in human neuroblastoma cell lines." (PMID 32840881, 2021). "Altered expression of PcG proteins, such as EZH2, SUZ12 and BMI1, are found in numerous cancer types, such as prostate, breast, liver and neuroblastomas, to name a few." (PMID 33912356, 2019). "Another study demonstrated that Bmi-1 is not only required for their clonogenic self-renewal of I-type neuroblastoma cells, but also regulates their lineage-specific differentiation in a concentration dependent manner." (PMID 22844494, 2012). "In support of this, studies in neuroblastoma have observed that MYCN functionally cooperates with Twist-1 or BMI-1 to induce neuroblastoma tumorigenesis, where overexpression of Twist-1 or BMI-1 is necessary for tumor growth both in vitro and in vivo." (PMID 23226679, 2012). "Bmi1 overexpression has been reported in several different tumor types including medulloblastoma and neuroblastoma." (PMID 19823589, 2009). "Other studies also demonstrated that Bmi-1 regulates the differentiation and clonogenic self-renewal of I-type neuroblastoma cells." (PMID 21637439, 2009). "On the other hand, loss of Bmi-1 with RNA interference (RNAi) was effective in suppressing growth and tumorigenicity of cancer cells (such as SH-SY5Y neuroblastoma and ovary adenocarcinoma)." (PMID 21637439, 2009). "Our result is consistent with a recent report demonstrating cancer-specific cytotoxic effect of Bmi-1 knockdown in neuroblastoma cells." (PMID 17179983, 2007). "Recent studies showed that Bmi-1 is a direct transcriptional target of c-Myc in human fibroblasts and of E2F-1 in neuroblastomas." (PMID 17179983, 2007). "Moreover, MYCN and MYC directly influence tumor proliferation and tumorigenesis through BMI1 in human neuroblastomas." (PMID 40862719, 2025). "Nowak reported that E2F1 and MYCN promote the transcription of Bmi1 in neuroblastomas." (PMID 33014838, 2020). "BMI1 is highly expressed in human neuroblastomas and neuroblastoma cell lines." (PMID 31856871, 2019). "Moreover, BMI1 was shown to cooperate with MYCN in the transformation of benign S-type neuroblastoma cells." (PMID 31856871, 2019). "miR-128 inhibits cell proliferation by targeting Bmi-1 to suppress neuroblastoma cell motility." (PMID 29445170, 2018). "Upregulation of cyclin E contributes to BMI1-promoted neuroblastoma progression." (PMID 26633535, 2015). "In neuroblastoma, PTC596-induced BMI1 inhibition depletes glutathione, enhances peroxide production and lipid peroxidation, and triggers ferroptosis." (PMID 40623983, 2025).
neuroblastoma (continued). "Most importantly, R+D ‘pre-treatment’ compared to control (vehicle) treatment proficiently reduced the elevated CXCR4, BMI1 and NANOG protein expression in spheroid cultures in both neuroblastoma cell lines." (PMID 36980635, 2023). "Besides, E2F1 could bind to the promoter of BMI1 to initiate its transcription in neuroblastomas." (PMID 33986804, 2021). "For example, BMI1, a core component of the PRC1 complex, has been shown to cooperate in MYCN-driven neuroblastomas by inhibiting cell death and differentiation." (PMID 34638328, 2021). "BMI-1 is a direct transcriptional target of c-MYC and MYCN and is overexpressed in ~90% of neuroblastoma, correlating with MYCN expression." (PMID 23226679, 2012). "Moreover, acute cisplatin treatment increased VEGF expression together with expression of the stemness genes Nanog, Bmi-1, and Oct 4 in osteosarcoma (HOS), rhabdomyosarcoma (RH-4) and neuroblastoma (SK-N-BE2) cell lines." (PMID 19788758, 2009). "In this context, our previous studies demonstrated that an etoposide-resistant human neuroblastoma (NB) cell line displays high levels of GSH and shows a mono-allelic deletion of the 13q14.3 locus that leads to miRNA 15a/16-1 downregulation and the consequent overexpression of BMI-1." (PMID 38275623, 2023). "In fact, BMI1 expression, a gene, whose suppression resulted in significantly greater inhibition of cell growth, correlated with MYCN levels in MYCN-amplified neuroblastoma cells, and with MYC levels in the MYCN-nonamplified group." (PMID 30134948, 2018). "Although CHD5 has been shown to repress another PcG protein in neuroblastoma, BMI1 (a core component of PRC1), we did not observe an influence of CHD5 on BMI1 expression in HCC cells (data not shown)." (PMID 26517514, 2015).
pancreatic cancer (37 papers, 2012 to 2025). "In a preliminary study, we also found that hypoxia promotes the expression of CSC-associated markers Bmi1 and Sox2 in pancreatic cancer cells." (PMID 30486896, 2018). "Our results revealed that low-dose gemcitabine treatment (1–5 μM) for 24 h, which has a minimal killing effect on pancreatic cancer cells, induced the expression of stemness-associated molecules Bmi1 and Sox2 as well as the CSC marker CD24." (PMID 30486896, 2018). "CSC-associated markers Bmi1 and Sox2 sufficiently enhance self-renewal and dedifferentiation and endow pancreatic cancer cells with stemness." (PMID 30486896, 2018). "In this study, we explored a potential role for Bmi1 in mediating response that protects pancreatic cancer cells from the cytotoxic effect of gemcitabine via employing a loss of function approach through Bmi1 knockdown." (PMID 27177084, 2016). "In our study, we found that up-regulated expression of BMI-1 was associated with tumor invasion, metastasis and poor survival of pancreatic cancer patients." (PMID 26840020, 2016). "Loss-of-function of Bmi1 in pancreatic cancer cells was achieved by siRNA knockdown." (PMID 27177084, 2016). "Overexpression of BMI-1 could stimulate malignant transformation, proliferation, invasion, distant metastasis and was associated with poor patient survival in various human cancers, including pancreatic cancer." (PMID 26840020, 2016). "High glucose is also able to inhibit AMP-activated protein kinase signaling, leading to high expression of Bmi1, which promotes immune escape in pancreatic cancer cells." (PMID 40630951, 2025). "Immune escape of pancreatic cancer cells from NK cell-mediated elimination in a hyperglycemic tumor microenvironment was also shown to be mediated by upregulation of Bmi-1 and subsequent MICA/B inhibition and GATA2 promotion." (PMID 36726797, 2023). "Surprisingly, SOX9 overexpression did not alter the expression of SNAIL or other well-known EMT transcription factors such as SLUG or ZEB1 in BxPC-3 and IMIMPC-2 pancreatic cancer cells; however, the expression of the BMI1 stem cell factor was elevated." (PMID 35205666, 2022). "The overexpression of miR-15a in pancreatic cancer cells reduces the expression of BMI-1, and similarly, the overexpression of miR-195 (a member of the miR-15 family) inhibits DCLK1 expression." (PMID 33562727, 2021). "The ZEB1/miR-200/BMI1 pathway was involved in pancreatic cancer stem cells, which explained how EMT enabled stemness." (PMID 34178686, 2021). "These key markers for stemness, such as BMI-1 expression, are correlated with poorer prognosis in pancreatic cancer patients that have undergone surgical resection." (PMID 33562727, 2021). "We started with pancreatic cancer CSCs (PANC-1 CSLC and PSN-1 CSLC) and determined the effect of dexamethasone on the expression of stem cell–associated markers (CD133, Sox2, Nanog, Bmi1, and Nestin) and the differentiation marker E-cadherin." (PMID 33115754, 2020). "To further test this idea, we lentivirally transduced a construct encoding BMI1 gene in MKN45 GC cells and Panc-1 and RWP-1 pancreatic cancer cells with SOX9 knockdown or controls." (PMID 31941916, 2020). "On the other hand, the cytotoxicity of NK cells on pancreatic cancer cells increased when Bmi1 was inhibited with siRNA transfection." (PMID 31088566, 2019). "We further explored the effect of Bmi1 overexpression on NK cell cytotoxicity on pancreatic cancer cells." (PMID 31088566, 2019). "We previously reported that overexpression of Bmi1 promotes proliferation, malignant transformation, and is related to a poor survival of pancreatic cancer." (PMID 31088566, 2019). "Bmi1 has been proven to be an important factor in promoting the chemoresistance of pancreatic cancer cells induced by gemcitabine." (PMID 31244991, 2019). "SiRNA was used for silencing Bmi1, and the invasion and migration of pancreatic cancer cells were further investigated." (PMID 31244991, 2019).